ASTN2 (astrotactin 2)
Description:
Mediates recycling of the neuronal cell adhesion molecule ASTN1 to the anterior pole of the cell membrane in migrating neurons. Promotes ASTN1 internalization and intracellular transport of endocytosed ASTN1 (By similarity). Selectively binds inositol-4,5-bisphosphate, inositol-3,4,5-trisphosphate and inositol-1,3,4,5-tetrakisphosphate, suggesting it is recruited to membranes that contain lipids with a phosphoinositide headgroup (Ref.6).
Synonyms: KIAA0634; bA67K19.1
Tractability: Antibody: UniProt predicts a signal peptide or a membrane-spanning region. PROTAC: ubiquitination databases record sites on it; its protein half-life has been measured.
Gene: Protein-coding gene on chromosome 9 (116,423,112 to 117,415,070, reverse strand). Ensembl gene ENSG00000148219.
Subcellular location: Membrane; Perikaryon; Cytoplasm, cell cortex; Early endosome; Late endosome; Cytoplasmic vesicle, clathrin-coated vesicle; Cytoplasmic vesicle
Subcellular location (Human Protein Atlas): Cytosol; Nucleoplasm
Gene Ontology:
Molecular function: calcium ion binding; inositol 1,3,4,5 tetrakisphosphate binding
Biological process: neuron cell-cell adhesion; neuron migration
Cellular component: cytoplasmic vesicle; early endosome; endosome; late endosome; membrane; perikaryon; cell cortex; cell pole; clathrin-coated vesicle
Genetic constraint (gnomAD): Loss-of-function variants: 50 observed, 133.85 expected, observed/expected ratio (o/e) 0.37, 90% interval 0.3 to 0.47. The upper end of that interval is the gene's LOEUF score, 0.47, which puts it in group 2 of 6, group 1 being the genes least tolerant of losing a copy. Missense variants: 1,485 observed, 1,634.8 expected, observed/expected ratio (o/e) 0.91, 90% interval 0.87 to 0.95. Synonymous variants: 701 observed, 674.82 expected, observed/expected ratio (o/e) 1.04, 90% interval 0.98 to 1.11.
Homologues: Orthologues: macaque ASTN2 (99% identical), mouse Astn2 (97% identical), pig ASTN2 (97% identical), rat Astn2 (97% identical), chimpanzee ASTN2 (96% identical), dog ASTN2 (95% identical), rabbit ASTN2 (89% identical), guinea pig ASTN2 (85% identical), tropical clawed frog astn2 (70% identical). Paralogues in human: ASTN1 (49% identical).